LCT (lactase)
Diseases named in the same sentence as LCT in open-access papers (continued):
Sharing a sentence is not in itself a finding about the gene and the disease.
Insulin resistance (1 paper, 2023). Increased resistance towards insulin, that is, diminished effectiveness of insulin in reducing blood glucose levels. "Furthermore, lactase non-persistence itself has been associated with insulin resistance." (PMID 37585412, 2023).
intrauterine growth restriction (1 paper, 2025). "Other studies with comparable methyl donor supplementation patterns have demonstrated a reduction in the incidence of intrauterine growth restriction (IUGR) in piglets and increased intestinal lactase and sucrase activity." (PMID 39858189, 2025).
major depression (1 paper, 2018). "All in all, 22/78 patients (28.2%) with PALM and 58/160 (36.3%) individuals with lactase persistence were diagnosed with major depression." (PMID 30138390, 2018). "Plasma levels of HCY, FA and vitamin B12 were determined in 78 patients with PALM and 160 individuals with lactase persistence sub-grouped by the presence or absence of major depression." (PMID 30138390, 2018). "The current work investigated 78 subjects with PALM and 160 individuals with lactase persistence sub-grouped by the presence or absence of major depression for their HCY, FA and vitamin B12 plasma levels." (PMID 30138390, 2018). "Therefore, this study was conducted to evaluate possible associations between HCY, FA and vitamin B12 plasma levels in 78 patients with PALM and 160 individuals with lactase persistence sub-grouped by the presence or absence of major depression." (PMID 30138390, 2018).
osteoporosis (1 paper, 2023). A condition of reduced bone mass, with decreased cortical thickness and a decrease in the number and size of the trabeculae of cancellous bone (but normal chemical composition), resulting in increased fracture incidence. "It was also noted that individuals with lactase deficiency were more likely to suffer from osteoporosis, however these values were not statistically significant compared with individuals with CT and TT genotypes." (PMID 37373338, 2023).
Overgrowth (1 paper, 2015). Excessive postnatal growth which may comprise increased weight, increased length, and/or increased head circumference. "Based on the 13C/H2 breath test, 314 patients were diagnosed with lactase deficiency, 138 with lactose malabsorption or small bowel bacterial overgrowth (SIBO), and 599 with normal lactose digestion." (PMID 26371034, 2015).
phenylketonuria (1 paper, 2019). Phenylketonuria (PKU) is the most common inborn error of amino acid metabolism and is characterized by mild to severe mental disability in untreated patients. "The concept of nutrigenetics is not entirely new, given the classic examples of phenylketonuria and lactase persistence." (PMID 31737029, 2019).
Plasmodium falciparum malaria (1 paper, 2005). Malaria resulting from infection by Plasmodium falciparum. "For example, the lactase gene (LCT, associated with lactose tolerance) has one of the highest relative extended haplotype homozygosity (rEHH) scores in the CEU population, as does the beta-globin gene (HBB, associated with protection against Plasmodium falciparum malaria) in the YRI population." (PMID 16254603, 2005).
protein-energy malnutrition (1 paper, 2010). A nutritional deficit that is caused by inadequate protein or calorie intake. "Children with severe protein-energy malnutrition commonly have a reduced activity of intestinal lactase, the enzyme responsible for the digestion of lactose, and it has been suggested that feeding this disaccharide can retard nutritional recovery." (PMID 20459633, 2010). "A combination of nutritional injury and infectious insults in severe protein energy malnutrition reduces the capacity of the intestinal mucosa to produce lactase enzyme necessary for the digestion of lactose." (PMID 20459633, 2010).
psychosis (1 paper, 2012). "A number of the genes in these categories, including LCT, have been previously directly implicated in the etiology of schizophrenia and psychosis." (PMID 22363459, 2012).
Salmonella gastroenteritis (1 paper, 2018). Poisoning caused by ingestion of food harboring species of salmonella. "The major strength of this study is that this is the first report of relatively common secondary lactase deficiency in children with nontyphoidal Salmonella gastroenteritis." (PMID 29686701, 2018). "Our study showed that 28.9% of children had significant symptom improvement with a lactose-free formula or diet, indicating that secondary lactase deficiency occurs frequently in children with nontyphoidal Salmonella gastroenteritis." (PMID 29686701, 2018).
virus infection (1 paper, 2016). "Down-regulation of transporter related genes, such as lactase-phlorizin hydrolase (LPH), B(0,+)-type amino acid transporter 1 (BAT1), actin cytoskeleton-regulatory complex protein PAN1 (PAN1), MFS-type transporter (MFS), and otoferlin, could repress virus infection in host cells." (PMID 27168061, 2016).
vitamin D deficiency (1 paper, 2023). A nutritional condition produced by a deficiency of VITAMIN D in the diet, insufficient production of vitamin D in the skin, inadequate absorption of vitamin D from the diet, or abnormal conversion of vitamin D to its bioactive metabolites. "Our study contributes to understanding the prevalence of genetic variants related to lactase non-persistence and vitamin D deficiency in the Chilean IBD cohort, highlighting its potential implications for disease management and identifying other causes of symptoms." (PMID 37834314, 2023).
cancer (4 papers, 2013 to 2021). A tumor composed of atypical neoplastic, often pleomorphic cells that invade other tissues. "Since many studies have indicated that the high level of lactase is closely associated with major hallmarks of cancer." (PMID 33726814, 2021). "In the second part, a possible association of lactase persistent or lactase non-persistent phenotypes with the incidence of some common types of cancer is reviewed." (PMID 26343715, 2015).
cardiovascular disease (4 papers, 2008 to 2023). "Two of the genes we selected to this study, LCT and APOBEC2, have not been previously associated with molecular pathogenesis of cardiovascular disease." (PMID 18974842, 2008).
tumor (4 papers, 2008 to 2023). "The number of LCT C and CaSR S risk alleles were associated with increasing tumor incidence (p = 0.035)." (PMID 18980667, 2008).
genetic disorder (3 papers, 2009 to 2019). "Congenital lactase deficiency (CLD) is a severe autosomal recessive genetic disorder that affects the functional capacity of the intestinal protein lactase-phlorizin hydrolase (LPH)." (PMID 30813293, 2019). "Primary lactase deficiency can be regarded as the commonest “genetic disease” in the World, although, in truth, loss of lactase expression in adulthood represents the normal “wild-type” and lactase persistence the abnormal “mutant” state." (PMID 26393648, 2015).
digestive system diseases (2 papers, 2024). "These proteins consist of lipases, lactase, hormones, interleukins, molecules that stimulate local immune responses, and proteins capable of preventing digestive system diseases." (PMID 39458526, 2024). "Two main groups of treatment were initially defined based on genetic characteristics as they are possible primary and irreversible causes of gastrointestinal disorders: (a) lactase non-persistence (LNP) condition and (b) HLA of risk or genetic predisposition to CD." (PMID 39203877, 2024).
infection (2 papers, 2015 to 2024). The state of being infected such as from the introduction of a foreign agent such as serum, vaccine, antigenic substance or organism. "Additionally, in secondary lactase deficiency, the ability to digest lactose can be lost due to infection, surgery and other insults." (PMID 26393648, 2015).
cardiac diseases (1 paper, 2012). "Our analysis suggest that the identified regions harbor known and novel genetic polymorphisms responsible for the unusual lipid metabolism, cholesterol homeostasis, protection against cardiac diseases and adult lactase persistence in the Maasai." (PMID 23028602, 2012).
LCT also shares sentences with these, for which no sentence is quoted: adenocarcinoma of the lung (2 papers); Adult-type hypolactasia (2); anaphylaxis (2); multiple sclerosis (2); nephrocalcinosis (2); type 2 diabetes (2); abetalipoproteinemia (1); adenocarcinoma of the breast (1); age (1); astrocytoma of the brain (1); autoimmune disease (1); bacterial infections (1); beta-thalassaemia (1); cognitive decline (1); colon cancer (1); coronary heart disease (1); cyst (1); diabetic retinopathy (1); diarrheal disease (1); dyskeratosis congenita (1); Epileptic encephalopathy (1); fructose intolerance (1); gastrointestinal disease (1); hepatocellular carcinoma (1); Hypercalcemia (1); hyperlipidemia (1); Hypertension (1); inflammation (1); ischemic stroke (1); lung carcinoma (1).
A further 17 diseases each share a sentence with LCT in 1 paper.